FABP7 (fatty acid binding protein 7)
Diseases named in the same sentence as FABP7 in open-access papers (continued):
Sharing a sentence is not in itself a finding about the gene and the disease.
low grade glioma (2 papers, 2024 to 2025). A grade I or grade II glioma arising from the central nervous system. "FABP7 expression is significantly associated with reduced immune cell infiltration and shortened survival in low-grade glioma (LGG) patients." (PMID 40717587, 2025). "Furthermore, FABP7 expression is significantly linked to reduced immune cell infiltration and shorter survival in low-grade glioma (LGG) patients." (PMID 40717587, 2025).
multiple sclerosis (2 papers, 2025). A progressive autoimmune disorder affecting the central nervous system resulting in demyelination. "FABP7‐knockout (FABP7‐KO) in mice led to an increase in the mRNA levels of IL‐17 and TNF‐α within the lesioned regions in a mouse model of multiple sclerosis (MS)." (PMID 40331773, 2025).
multiple system atrophy (2 papers, 2023). Multiple system atrophy (MSA) is a neurodegenerative disorder characterized by autonomic failure (cardiovascular and/or urinary), parkinsonism, cerebellar impairment and corticospinal signs with a median survival of 6-9 years. "In addition, regarding FABP7, the ligand alleviates FABP7-induced α-synuclein oligomerization and aggregation, thereby rescuing glial and oligodendrocytes from cell death in multiple system atrophy model cells and mice." (PMID 38069360, 2023). "Furthermore, FABP7 contributes to the accumulation of α-synuclein in mitochondria in oligodendrocytes to lose the membrane potential in the multiple system atrophy model mice." (PMID 38069360, 2023).
psoriasis (2 papers, 2022 to 2024). An autoimmune condition characterized by red, well-delineated plaques with silvery scales that are usually on the extensor surfaces and scalp. "FABP-7 concentrations were higher in subgroups with more intense psoriasis severity expressed by PASI, although the significant difference between the groups was observed only between PASI III and controls." (PMID 35566558, 2022). "Psoriasis severity seems to not affect the risk of NDs, however cognitive impairment might be more prevalent in severe psoriatics and FABP-7 and NFL could be a biomarker for them." (PMID 35566558, 2022). "Moreover, it appears that the time of suffering from psoriasis does not influence FABP-7 concentrations in patients, so the potential risk of NDs development is independent of the psoriasis duration and other factors that affect these relationships." (PMID 35566558, 2022). "The FABP-7 concentration was higher in patients with long-lasting psoriasis, although we did not observe any significant changes or correlations inside these subgroups (NS)." (PMID 35566558, 2022). "Serum concentrations of fatty acid-binding protein 7 (FABP-7), glutamic acid (GA) and neurofilament light chain (NFL), which have been hardly studied in psoriasis before, were measured by ELISA before and after 12 weeks of treatment with acitretin or methotrexate." (PMID 35566558, 2022).
schwannoma (2 papers, 2013 to 2017). A benign, usually encapsulated slow growing tumor composed of Schwann cells. "Schwannoma tumorlets in the DRGs of mGFAP-Cre;Smarcb1flox/flox;Nf2flox/flox mice were negative for SMARCB1 and merlin staining, about 60% were positive for S100 protein staining, and all were positive for GFAP and FABP7." (PMID 28824165, 2017).
Sepsis (2 papers, 2020 to 2021). Sepsis is defined as life-threatening organ dysfunction caused by a dysregulated host response to infection. "Among that, Lrp5, Cyp7a1, Nfkbiz, Sigmar1, Fabp7, and Hao1 have been reported in the inflammatory response and lipid metabolic process, suggesting that these genes may play an important role in modulating sepsis-induced system inflammation in WT and LBP-deficient rats after LPS injection." (PMID 35005033, 2021).
viral infection (2 papers, 2024 to 2026). "First, we generated U6‐Fabp7 shRNA encoded by AAV2/9 and measured the level of the Fabp7 mRNA using qPCR, and its expression was notably downregulated in cultured primary mouse cortical progenitors after virus infection." (PMID 39556706, 2024).
acute liver failure (1 paper, 2017). Rapid deterioration of liver function causing encephalopathy and coagulopathy. "This nested case–control study of randomly selected samples from prospectively enrolled patients from the US Acute Liver Failure Study Group (ALFSG) registry aimed to examine levels of FABP7 in APAP-ALF patients." (PMID 28983815, 2017). "Nonetheless despite these limitations, we believe these results are robust as they include APAP-ALF cases from across 16 tertiary liver transplant centers comprising the US ALFSG and are the first report of FABP7 in acute liver failure." (PMID 28983815, 2017).
Alexander disease (1 paper, 2023). Alexander disease (AxD) is a rare neurodegenerative disorder of the astrocytes comprised of two clinical forms: AxD Type I and Type II manifesting with various degrees of macrocephaly, spasticity, ataxia and seizures and leading to psychomotor regression and death. "In an unbiased proteomics screen, hippocampal FABP7 was elevated in a mouse model of Alexander disease (AxD), and in AxD patient brain tissue." (PMID 37404868, 2023).
amyloid (1 paper, 2024). "In addition, we observed an increase of about 70% in FABP7 staining intensity in GFAP+ astrocytes located in the vicinity of amyloid plaques (within 50 μm from the edge of a plaque) when compared to non-plaque-associated astrocytes (located at a distance > 50 μm from the edge of a plaque)." (PMID 37688656, 2024).
anaplastic astrocytoma (1 paper, 2022). "Then, we investigated FABP7 expression and localization using patient samples with diffuse astrocytoma, anaplastic astrocytoma, and GB which were diagnosed with IDH1wt or IDH1mut." (PMID 34716958, 2022). "Notably, immunohistochemistry revealed a high expression of FABP7 in both cytoplasm and nucleus of IDH1wt GB and in nucleus of IDH1wt anaplastic astrocytoma, while IDH1mut samples expressed lower level of FABP7 without expression in nucleus." (PMID 34716958, 2022).
anaplastic glioma (1 paper, 2022). "Consistently with database analysis, western blot demonstrated higher expression level of FABP7 in IDH1wt GB than in IDH1mut diffuse glioma, anaplastic glioma, and GB." (PMID 34716958, 2022).
anxiety disorder (1 paper, 2022). A category of psychiatric disorders which are characterized by anxious feelings or fear often accompanied by physical symptoms associated with anxiety. "Fatty acid binding protein 7 (FABP7) is critical in hippocampal neurogenesis and is closely related to neuropsychiatric diseases, including anxiety disorder." (PMID 36299292, 2022).
Ataxia (1 paper, 2022). Ataxia refers to impaired coordination of voluntary muscle movement. "Similarly, astrocyte-specific deletion of Kcnj10 using GFAP-cre mice results in premature lethality, epileptic seizures, and severe ataxia, none of which were observed with Kir4.1 deletion using Fabp7-CreER2 mice." (PMID 35997251, 2022).
Autoimmunity (1 paper, 2022). The occurrence of an immune reaction against the organism's own cells or tissues. "FABP7 is thus known to be present in areas of inflammation in MS, and FABP7 autoimmunity could potentially contribute to remyelination failure." (PMID 35476434, 2022).
cardiomyopathy (1 paper, 2025). A disease of the heart muscle or myocardium proper. "Similar to that in the bag3 cardiomyopathy model, the expression of Fabp7 protein level was also increased during normative cardiac aging in the killifish." (PMID 40922543, 2025).
cognitive decline (1 paper, 2025). "In AD, FABP7 expression is upregulated in astrocytes around amyloid plaques, while ApoE4 disrupts myelin homeostasis in the frontal cortex by altering ApoE and FABP7, contributing to early demyelination and cognitive decline." (PMID 41154661, 2025).
cutaneous squamous cell carcinoma (1 paper, 2023). "In human skin cell carcinomas, FABP7 levels were reduced relative to control patient samples, and overexpression of FABP7 in cutaneous squamous cell carcinoma cell lines inhibited proliferation, invasiveness, and migration, with effects shown to be dependent on Notch signaling." (PMID 37207357, 2023).
Fibroadenoma (1 paper, 2016). A benign tumor of the breast characterized by the presence of stromal and epithelial elements. "In a separate study by Kuijper interrogating the transcriptome differences between five fibroadenomas and eight phyllodes tumors, CTAG1/2, PRAME, HOXC13, ELF5 and FABP7 were among 96 other transcripts found to be highly differentially expressed between fibroadenomas and phyllodes tumors." (PMID 26961242, 2016).
fibrosis (1 paper, 2025). the formation of excess fibrous connective tissue in an organ or tissue in a reparative or reactive process. "Interestingly, serum CCL17 levels were lower in Fabp7−/− mice than in WT mice in both the CT and fibrosis groups." (PMID 40017805, 2025).
hearing loss (1 paper, 2023). "To investigate the involvement of FABP7 in noise-induced hearing loss (NIHL) pathogenesis, we used Fabp7 knockout (KO) mice generated via CRISPR/Cas9 in the C57BL/6 background." (PMID 38057582, 2023).
insomnia (1 paper, 2023). A sleep disorder characterized by difficulty in falling asleep and/or remaining asleep.
intracranial aneurysms (1 paper, 2023). "In summary, the findings of our study indicate that endovascular treatment of intracranial aneurysms has a significant impact on the serum levels of NFL, GP39, hsCRP, and FABP7." (PMID 37759909, 2023).
leprosy (1 paper, 2022). Leprosy is a chronic infectious disease affecting primarily the skin and peripheral nervous system. "We also described a molecular signature associated with neural damage in early stages of pure neural leprosy from patients (i.e., HLA-DRB1, MAPK14, GAP43, FABP7, NTN1, and LRRTM4)." (PMID 35492305, 2022).
Lewy body diseases (1 paper, 2023). "The intricate involvement of FABPs, particularly FABP3, FABP5, and FABP7, in the pathogenesis of Lewy body diseases highlights their significance in reflecting the disease state." (PMID 37686075, 2023). "Additionally, FABP7 is expressed in oligodendrocytes, which are myelin-producing cells that accumulate α-synuclein and contribute to Lewy body disease pathology." (PMID 37686075, 2023).
liver diseases (1 paper, 2025). "Therefore, regulation of hepatic macrophage function by modulating FABP7 expression and ligand binding is a promising target to treat liver diseases and maintain liver homeostasis." (PMID 40017805, 2025).
lymphoma (1 paper, 2020). A malignant (clonal) proliferation of B- lymphocytes or T- lymphocytes which involves the lymph nodes, bone marrow and/or extranodal sites. "Both lymphomas and carcinomas expressed H3.3K27M and FABP7, indicating that they were driven by transgene expression rather than forming spontaneously." (PMID 33277484, 2020).
meningioma (1 paper, 2020). A generally slow growing tumor attached to the dura mater. "Taken together, these findings provide a strong rationale to investigate the potential role of FABP7 in meningioma pathogenesis." (PMID 33167358, 2020). "Moreover, two previous studies have reported a significant correlation between increasing FABP7 expression and increasing meningioma grade following IHC." (PMID 33167358, 2020). "Yet, following FABP7 depletion in several cancer cell lines, proliferation and migration are reduced, inferring that exploring FABP7 inhibitors may hold promise as a future targeted therapy of meningioma." (PMID 33167358, 2020).
metastasis (1 paper, 2011). The spread or migration of cancer cells from one part of the body (where they first appeared) to another. "Furthermore, ACHN and Caki-1 cell line, which expressed FABP7 mRNA weaker than other, isolated from malignant pleural effusion and cutaneous metastasis each." (PMID 21771320, 2011).
non-alcoholic fatty liver disease (1 paper, 2018). "Dysregulation was established for FABP3 in cardiovascular disorders, FABP1, FABP2, FABP4 and FABP5 in non-alcoholic fatty liver disease and FABP5 and FABP7 in cancer." (PMID 30386187, 2018).
oligodendroglial tumor (1 paper, 2006). Oligodendrogliomas are cerebral tumors that are differentiated from other gliomas on the basis of their unique genetic characteristics and better response to chemotherapy. "An immunoblot of extracts from two GBM specimens and two oligodendroglial tumors showed detectable levels of FABP7 protein." (PMID 16623952, 2006).
pilocytic astrocytoma (1 paper, 2006). Pilocytic astrocytoma is a rare subtype of low-grade glioma of the central nervous system characterized by a well circumscribed, often cystic, brain tumor with a discrete mural nodule and long, hair-like projections that extend from the neoplastic astrocytes. "Although our size of sampling was limited, the statistical analyses clearly demonstrate that the chance of detecting nuclear FABP7 in pilocytic astrocytoma is small." (PMID 16623952, 2006). "We also examined 10 pilocytic astrocytoma specimens (grade I), and, in agreement with previous gene expression profiling of this type of tumor, 9 of our specimens were positive for FABP7." (PMID 16623952, 2006).
retinal degeneration (1 paper, 2022). Degeneration of the retina. "Moreover, we found transcriptional deregulation of two other genes, Reep6 and Fabp7, which have been linked directly to retinal degeneration." (PMID 35626712, 2022).
systemic lupus erythematosus (1 paper, 2015). An autoimmune multi-organ disease typically associated with vasculopathy and autoantibody production. "It has also been described for HERV-E.FABP7 in leukemic B cells; HERV-E.PTN, HERV-E.EDNRB, and HERV-E.MID1 in placenta but not in blood cells; and HERV-E clone 4-1 in peripheral blood lymphocytes (CD4+, CD8+ and B cells) but not in neutrophils from patients with systemic lupus erythematosus (SLE)." (PMID 25785516, 2015).
type 1 diabetes mellitus (1 paper, 2021). A chronic condition characterized by minimal or absent production of insulin by the pancreas. "FABP7 was significantly correlated with “breakdown of CD4+ T-cell peripheral tolerance in type 1 diabetes mellitus”, “immune response_IL-12 signaling pathway”, and “immune response_T-cell co-signaling receptors, schema” in CRC development." (PMID 34680577, 2021).
tumor (74 papers, 2005 to 2026). "metascape analysis of the three tumor proteins of interest indicated that FABP7, TJAP1 and AHSP were associated with fatty‐acid transport (GO:0015908), Golgi organization (GO:0007030) and hemoglobin metabolic process (GO:0020027), respectively." (PMID 38803161, 2024). "By driving the expression of onco-immune modulatory genes, such as ENO1, MUC1, COL5A1, and IL11, FABP7 enhances tumor-associated immune suppression, particularly by facilitating the infiltration of immunosuppressive cell populations within TIME." (PMID 39596296, 2024). "An association between FABP7 expression in colon cancer tissues and cell proliferation as well as tumor growth has been observed, with effects dependent on MEK/ERK signaling." (PMID 37207357, 2023). "To examine the role of FABP7 in tumor biology, we constructed loss of function model using IDH1wt U251 cells, which possess endogeneous FABP7." (PMID 34716958, 2022). "Another study demonstrated that a mutation in the lipid-binding domain eliminates both FABP7 lipid-binding capacity and its nuclear localization, consequently decreasing tumor proliferation." (PMID 32812201, 2020). "Other downregulated genes included fatty acid binding protein 7 (FABP7), previously linked to the proliferation, migration, and invasion of tumor cells, and cofilin 1 (CFL1), a central regulator protein of actin dynamics in migrating cells." (PMID 26918341, 2016). "FABP7 expression is also associated with increased cell migration and tumor invasiveness." (PMID 37207357, 2023). "Thus, further investigation on mechanisms underlying a tumor context-dependent role of FABP7 in formation of lipid droplets will be interesting and necessary." (PMID 35269427, 2022). "Given these correlations, FABP7 is thought to be one of the tumorigenesis markers, but the underlying mechanisms of FABP7 involvement in tumor proliferation are still unknown." (PMID 34716958, 2022). "Moreover, the doubling times of subclones of TUHR15TKB cells differed significantly, which is consistent with the loss of FABP7 expression during attempts to establish cell lines from primary RCC tumor tissue." (PMID 28292269, 2017). "We also evaluated the potential involvement of FABP7 in response to radiotherapy, as this treatment may cause increased tumor infiltration." (PMID 23284888, 2012). "Our present study identifies FABP7 as a metastatic tumor cell-specific pro-metastatic gene and uncovers a previously unknown regulatory mechanism underlying Wnt hyperactivation via FABP7-impaired cytoplasmic β-catenin degradation, implicating a novel molecule in regulating NSCLC metastasis." (PMID 35269427, 2022). "In addition, FABP7 expression is associated with proliferation and tumor thickness in the patients with SSM, suggesting that for these patients FABP7 could be a potential target for therapy." (PMID 18826602, 2008). "Knockdown of FABP7 reduces the migration and infiltration of tumor stem cells and enhances radiotherapy sensitivity." (PMID 40717587, 2025). "The combination of FABP7 with immune checkpoint inhibitors such as PD-1/PD-L1 can reverse tumor immune evasion and enhance therapeutic efficacy." (PMID 40717587, 2025). "In murine lung cancer cell lines, FABP7 enables tumor cells to evade immune cell-induced ferroptosis." (PMID 40919170, 2025). "Our findings demonstrated that FABP7-mediated lipid transfer from macrophages to tumor cells increased their dependence on mitochondrial fatty acid oxidation, thereby facilitating metastatic colonization." (PMID 40765822, 2025). "Conversely, FABP7 KO attenuated lipid transfer and diminished tumor cell proliferation, while reducing tumor cell death upon coculture." (PMID 40765822, 2025). "Clinical analysis revealed an inverse correlation between FABP7 expression and tumor-infiltrating CD8+ T cell (TIL) density in liver metastases from CRC patients." (PMID 40765822, 2025).